TNF (tumor necrosis factor)
Diseases named in the same sentence as TNF in open-access papers (continued):
Sharing a sentence is not in itself a finding about the gene and the disease.
Obesity (continued). "TNF-α is the primary pro-inflammatory cytokine produced by macrophages and monocytes, contributing to the pathogenesis of autoimmune diseases and acting as a metabolic messenger produced by adipose tissue, ultimately contributing to obesity-related metabolic diseases." (PMID 40805975, 2025). "However, TNF-α, which is more strongly linked to obesity severity and insulin resistance, showed no significant change three months post-treatment." (PMID 40422620, 2025). "The present study showed that children with comorbid asthma and obesity/overweight had higher IL-6, TNF-α, and leptin, and lower 25-(OH) D3, IL-10, and IL-13 than children with asthma alone, and had lower IL-10 and higher IL-6, IL-13, and leptin than children with obesity/overweight alone." (PMID 40083433, 2025). "Obesity contributes to this pro-inflammatory milieu by promoting the release of cytokines such as interleukin-6 (IL-6), tumor necrosis factor-alpha (TNF-α), and C-reactive protein (CRP), which may adversely affect both the synovial environment and the fibrotic response within the joint capsule." (PMID 41007680, 2025). "Obesity is characterized by a chronic low-grade inflammation that affects thyroid function through excess cytokines and inflammatory markers—such as interleukin-1 (IL-1), interleukin-6 (IL-6), and tumor necrosis factor-alpha (TNF-alpha)—produced by enlarged adipose tissues." (PMID 41477173, 2025). "Thus, the plasma TNF-α level is considered an unreliable marker of tissue inflammation in obesity." (PMID 41463113, 2025). "In obesity, insulin resistance and T2D, PA-induced activation of monocyte/macrophages enhances the production of inflammatory cytokines like tumor necrosis factor-alpha (TNF-α) and Interleukin (IL)-1β, and dysregulates key macrophage functions implicated in inflammatory cardiometabolic diseases." (PMID 40068774, 2025). "It has also been determined that obesity, both in children and adults, induces a state of low-grade inflammation and metabolic alterations, such as increased plasma leptin, hyperinsulinemia, and elevated production of tumor necrosis factor-alpha (TNF-α) and interleukin-6 (IL-6), among others." (PMID 40531756, 2025). "Besides augmenting mechanical stress, obesity often correlates with chronic, low-grade inflammation, which heightens the activity of proinflammatory cytokines (e.g., TNF-α, IL-6), exacerbating ECM breakdown and reduced proteoglycan/collagen synthesis in the disc." (PMID 40421015, 2025). "Considering our findings (reduction in TNF-α without alterations in IL-6), we can suggest that ST may have partially attenuated the obesity-associated inflammatory state without impacting the secretion of pro-metabolic myokines." (PMID 40862455, 2025). "Thus, the tendency toward higher insulin levels in subjects with obesity carrying the A allele of the TNF-α gene, compared to those with the GG genotype, has not been universally observed." (PMID 40732969, 2025). "A dysbiosis in the gut microbiome as the result of obesity leads to a change in metabolites such as SCFA that cause a pro-inflammatory state characterized by increased levels of pro-inflammatory cytokines such as IL-1, IL-6, and TNF-α, the so-called “inflammatory triad”." (PMID 40551741, 2025). "Furthermore, TNF-α promotes the development of insulin resistance and obesity." (PMID 41156096, 2025). "In obesity, macrophages infiltrating adipose tissue form corona-like structures surrounding adipocytes, leading to the overproduction of adipokines, which comprise pro-inflammatory mediators, such as interleukin-1β (IL-1β), interleukin-6 (IL-6), and tumor necrosis factor-alpha (TNF-α)." (PMID 40427531, 2025). "Tumor necrosis factor (TNF), the first pro-inflammatory cytokine produced in the adipose tissue, acts as a catabolic mediator promoting the production of other pro-inflammatory cytokines, adipokines (such as leptin) and chemokines that cause obesity-associated metaflammation." (PMID 39837875, 2025).
Obesity (continued). "The marked upregulation of TNF-α in adipose tissue during obesity is a well-established marker of adipose tissue dysfunction and insulin resistance, and its attenuation by Andrographolide may contribute to the observed effects on glucose metabolic regulators in VAT." (PMID 40825507, 2025). "As obesity progresses, the adipokine secretion profile becomes imbalanced, with increases in pro-inflammatory molecules such as resistin, tumor necrosis factor-alpha (TNF-α) and interleukin-6 (IL-6) among others and decreases in protective molecules like adiponectin, omentina-1, etc.." (PMID 41155642, 2025). "Anti-TNFα therapy may be an optional therapy for obesity-related SAP." (PMID 39856555, 2025). "For instance, obesity-related factors such as elevated levels of pro-inflammatory cytokines (e.g., IL-6, TNF-α) and adipokines (e.g., leptin) may promote an immune-stimulatory environment that facilitates a stronger anti-tumor response when ICIs are administered." (PMID 40040878, 2025). "Given the increased expression of TNF and IL-6 noted in mice with high-fat diet-driven obesity phenotype, it is assumable that the inflammation observed in AO rats might be related to their proneness to obesity." (PMID 40177400, 2025). "Obesity, especially the VSF compartment, has been associated with a low-grade chronic inflammatory state due to the activation of the non-specific immune system, which increases the production of pro-inflammatory cytokines such as tumor necrosis factor-alpha and Interleukin-6." (PMID 39578337, 2025). "In addition, a recent study has revealed the interaction between ferroptosis and TNF-α and its impact on osteogenesis and angiogenesis, which might be related to the pathogenesis and regenerative therapy of obesity-related osteoporosis." (PMID 40344912, 2025). "Obesity contributes to a pro-inflammatory state that exacerbates psoriasis by secreting adipokines, such as leptin and resistin, which stimulate Th17 and Th1 cells, thereby increasing Il-17 and TNF-a cytokines, key factors involved in the pathogenesis of psoriasis." (PMID 40003621, 2025). "In this study, we aimed to evaluate whether TNFα, fibrinogen, cortisol, and anxiety mediate the relationship between BMI z‐score and EF in a sample of adolescents and adults ranging in BMI from normal‐weight to obesity." (PMID 40650919, 2025). "In addition, Polydatin also exerts anti-inflammatory effects in mature adipocytes, which may involve reduced expression of MCP-1 and TNF-α, implicating a potential anti-obesity effect." (PMID 40707685, 2025). "While some studies associate Blautia with metabolic disorders such as obesity and type 2 diabetes, others suggest its beneficial role in reducing inflammation, as evidenced by its negative correlation with fecal TNF-α levels in normal-weight children." (PMID 41140399, 2025). "Obesity, with its characteristic dysfunctional adipose tissue and adipokine dysregulation, creates chronic systemic inflammation characterized by elevated circulating IL-6, TNF-α, and other pro-inflammatory cytokines that act as paracrine and endocrine signals influencing prostate tissue." (PMID 41555998, 2025). "Furthermore, obesity can reduce the effectiveness of TNF inhibitors in treating RA46." (PMID 40087374, 2025). "Furthermore, obesity‐induced inflammation results in the production of pro‐inflammatory cytokines, such as interleukin‐6 (IL‐6), tumor necrosis factor‐alpha (TNF‐α), and C‐reactive protein (CRP), which contribute to an inflammatory TME conducive to cancer progression." (PMID 40922069, 2025). "However, treatment with an anti-TNF-α antibody could mitigate the host response to P. gingivalis and reduce serum TNF-α, IL-6, blood glucose levels, and the size of the P. gingivalis inoculation lesion in a mouse model for type 2 diabetes and obesity." (PMID 41228440, 2025).
Obesity (continued). "Specifically, it downregulates pro-inflammatory cytokines (e.g., TNF-α, IL-1β, and IL-6) while upregulating anti-inflammatory IL-10 and tight junction proteins (e.g., ZO-1 and OCLN), thereby reducing systemic inflammation and metabolic endotoxemia associated with obesity." (PMID 41365537, 2025). "Elevated levels of interleukin-1β (IL-1β) and tumor necrosis factor-α (TNF-α), part of the inflammatory network linking these two conditions, persist even after periodontal treatment, with high salivary cytokine levels being linked to overweight and obesity risk." (PMID 40430061, 2025). "In the context of obesity, adipocytes undergo hypertrophy, which subsequently leads to an increased recruitment of immune cells, such as M1 macrophages, and inflammatory mediators within the tissue, including tumor necrosis factor alpha (TNF-α), interleukin 6 (IL-6), and interleukin 1β (IL-1β)." (PMID 41149048, 2025). "The inflammation hypothesis suggests that obesity is a chronic inflammatory state, and inflammatory factors such as TNF-α, interleukin-1β (IL-1β), and IL-6 can decrease tissue sensitivity to insulin and lead to pathological changes in pancreatic β-cell function." (PMID 40842495, 2025). "Additionally, the chronic low-grade inflammation in obesity, characterized by an increase in pro-inflammatory cytokines such as IL-6) and tumor necrosis factor-α, along with C-reactive protein, creates a state that may precipitate insulin resistance." (PMID 39996060, 2025). "However, human myotubes exposed to TNF-a show increased IL-6 secretion, suggesting that muscle may also contribute to increased circulating IL-6 levels in people with obesity and T2D." (PMID 40171198, 2025). "In addition, inflammatory cytokines associated with obesity-related immune responses, including TNF-α, IL-6, and IL-10, were not measured, limiting our understanding of the immunometabolic effects of LA-1." (PMID 40732971, 2025). "Moreover, obesity would alter levels of numerous molecules, such as TNFα, DKK1, sclerostin, IL-6, serotonin, and advanced glycation end products, which could inhibit osteoblastogenesis." (PMID 40685394, 2025). "With the progression of obesity, the increase in pro-inflammatory signals prompts M2-type macrophages to transform into an M1-type pro-inflammatory phenotype, inducing adipocytes to secrete pro-inflammatory cytokines such as TNF-α, thereby promoting inflammatory responses and IR." (PMID 40842495, 2025). "The association between increased mitophagy marker expression and heightened inflammation (as indicated by TNF-α) in our cohort with obesity is in line with the concept that chronic inflammation and oxidative stress are major drivers of mitochondrial turnover in obesity." (PMID 41334630, 2025). "While earlier studies in TNFα-receptor-deficient mice failed to support the concept that TNFα is a major contributor to obesity-associated insulin resistance, increasing evidence supports a positive correlation between TNF-α-induced insulin resistance, NF-κB signaling, and pathogenesis of T2DM." (PMID 40002359, 2025). "Obesity, frequently observed in individuals with HS, is accompanied by an altered production of adipokines, such as resistin and chemerin, as well as elevated inflammatory cytokines IL- 1β and TNF-α, which contribute to inflammatory processes and metabolic derangements." (PMID 40358870, 2025). "Obesity, a central driver, may result in adipose tissue dysfunction, leading to chronic, low-grade inflammation due to the secretion of pro-inflammatory cytokines, such as Tumor Necrosis Factor alpha (TNF-α) and interleukin-6 (IL-6)." (PMID 41406476, 2025). "The presence of obesity has been shown to be a pathological process that may induce oxidative stress due to the excretion of pro-inflammatory cytokines from adipocytes such as IL-6 and TNF-α." (PMID 40722609, 2025).
Obesity (continued). "Furthermore, obesity may also reduce the efficacy of biologics, particularly tumor necrosis factor α agents, by increasing drug clearance and distribution volume." (PMID 41060265, 2025). "However, in pathological conditions—such as obesity or metabolic syndrome—elevated leptin levels become pro-inflammatory, increasing the production of pro-inflammatory cytokines, such as TNF-α and IL-6, exacerbating vascular inflammation and contributing to the development of atherosclerosis." (PMID 40943241, 2025). "Obesity further contributes to systemic low-grade inflammation, especially via visceral fat accumulation and metabolic dysfunction, leading to increased levels of IL-6, C-reactive protein, and tumor necrosis factor-α (TNF-α), which can trigger or worsen airway hyperresponsiveness." (PMID 40933690, 2025). "Obesity induces macrophage infiltration into adipose tissue and dysregulated adipokine secretion, leading to persistent elevation of inflammatory cytokines such as interleukin-6 (IL-6), tumor necrosis factor-alpha (TNF-α), and C-X-C motif chemokine ligand 10 (CXCL10)." (PMID 41441521, 2025). "Clinical reviews further document an increased IL-10/TNF-α ratio in obesity as a homeostatic brake on inflammation, and inflamed adipose depots concurrently express other anti-inflammatory mediators (e.g., IL-19), underscoring the shift away from TNF-α secretion in advanced adiposity." (PMID 40559392, 2025). "In addition, we did not measure TNF-α concentrations, and this limited our evidence supporting the association between an epigenetic and clinical or biochemical phenotypes related to obesity." (PMID 38542788, 2024). "For instance, elevated levels of IL-6 have been positively correlated with the expansion of adipose tissue.TNF-α, IL-6, and IL-1β can enhance the inflammatory cascade reaction and promote inflammatory responses, which are considered key triggering factors for obesity-related complications." (PMID 38453770, 2024). "In this study, 6‐week‐old C57BL/6J male mice fed with HFD for 14 weeks showed increased obesity‐related indexes including alanine aminotransferase, aspartate aminotransferase, total cholesterol, total triglyceride, free fatty acids, lipopolysaccharides, IL‐6, and TNFα." (PMID 38479983, 2024). "However, another report has shown that the relationship between MMD and obesity is associated with the expression of the ring finger protein 213 (RNF213) gene and is particularly affected via tumor necrosis factor-alpha-mediated inflammation and insulin resistance in adipocytes." (PMID 39600783, 2024). "This suggests that higher IL‐6 and TNF‐α levels in PCOS may be associated with IR, HA and obesity." (PMID 39036884, 2024). "Therefore, we examined whether CK can lower the mRNA level of inflammatory cytokines such as TNFα and IL-6 to ascertain its impact on obesity-mediated inflammation." (PMID 39859981, 2024). "Therefore, this study aimed to analyze whether dietary factors involved in the methylation of tumor necrosis factor (TNF)-α are implicated in differential protein expression in people with normal weight and obesity." (PMID 38542788, 2024). "In addition, in obesity, pro-inflammatory mediators (leptin, resistin, IL-6, and TNF-α) may promote adipose tissue dysregulation and systemic insulin resistance." (PMID 39065815, 2024). "Weight loss has been shown to reduce pro-inflammatory markers present in the chronic low-grade inflammatory state associated with obesity, including CRP, IL-6 and TNF-a (Christiansenet al., 2010;Marfellaet al., 2004;Moelleret al., 2016) and may thereby help manage LC symptoms." (PMID 39145102, 2024). "Tg, Tc, leptin, and TNF-α were positively correlated with denovo624899 abundance, indicating that denovo624899 in E. miletus may have a preference for high-fat foods, potentially contributing to obesity under conditions of high-fat food consumption." (PMID 39050639, 2024).
Obesity (continued). "Furthermore, in the context of metabolic disorders such as obesity, γδ17 cells have been observed to exacerbate inflammation and insulin resistance through heightened cytokine production, including IL-6 and TNF-α, and the recruitment of proinflammatory M1 macrophages." (PMID 38774876, 2024). "The accumulation of abnormal fat due to obesity leads to the impairment of white adipose tissue function, which is manifested by the increased production of specific pro-inflammatory proteins (such as adipokines) and cytokines (such as TNF) produced by immune cells in the matrix space." (PMID 39544385, 2024). "In addition, the volunteers with obesity showed higher ratios between IL-1β and IL-10 (A, p < 0.0001), IP-10 and IL-10 (D, p < 0.05), TNF-α and IL-10 (E, p < 0.0001), IL-12p70 and IL-10 (F, p < 0.01), IFN-γ and IL-10 (G, p < 0.05), and GM-CSF and IL-10 (H, p < 0.0001) than the NW group." (PMID 39125408, 2024). "Regarding inflammation, different kinds of cytokines, including interleukin-6 (IL-6), C-reactive protein (CRP), tumor necrosis factor α (TNF-α), as well as adipokines, may be involved in inflammatory pathways producing obesity and insulin resistance, triggering systemic stress." (PMID 38541047, 2024). "It has been documented that obesity in BC is directly linked with CRF, and this association is probably attributed to the high levels of circulating inflammatory cytokines, i.e., tumor necrosis factor-alpha (TNF-alpha) and interleukin-6 (IL-6), as well as blood fatty acid imbalance." (PMID 38398193, 2024). "Therefore, TNF-alpha is recognized as an important mediator linking obesity to insulin resistance." (PMID 39120321, 2024). "At the same time, the hyperactivation of glucocorticoid receptors can cause inflammatory response, which may explain why levels of the pro-inflammatory cytokines tumor necrosis factor-α and interleukin-6 were significantly higher in the presence of stress-induced obesity than in its absence." (PMID 39539712, 2024). "Indeed, obesity led to reduced expression of multiple DNA repair genes (mRNA array), which were further shown to be influenced by inflammation through in vitro experiments using tumor necrosis factor-α treatment on FT chorionic villous explants." (PMID 39092995, 2024). "In obesity, due to increased body mass, the adipose tissue is dysfunctional, with an altered expression of cytokines and adipokines; as a result, pro-inflammatory plasma levels of cytokines such as interleukin-6 and tumor necrosis factor alpha increase in obesity patients." (PMID 39596974, 2024). "In an in vitro model of obesity-associated cellular stress, exposure of preadipocytes and adipocytes to palmitate and TNF-α significantly increased markers of hypoxia (HIF-α, GLUT1, VEGF), ER stress (sXBP1, CHOP, BiP/GRP78), and inflammation (IL-6, MCP-1, and TNF-α)." (PMID 39063184, 2024). "It is also possible that this connects to increased disease severity after respiratory viral infections in people with heightened inflammation such as inflamaging or obesity, where cytokines such as IL-1α and TNF-α could be increased in the mucosa before infection." (PMID 39127259, 2024). "Furthermore, the chronic low‐grade inflammatory state in obesity results in the infiltration of immune cells, such as macrophages, into the pancreatic islets via the release of proinflammatory cytokines (e.g., TNF‐α and IL‐1β), which can impair β‐cell function and survival." (PMID 38812572, 2024). "Increasing numbers of M1 macrophages as well as activated adipocytes present in inflamed fat tissue produce TNF-α, IL-6 and other inflammatory mediators including leptin and resistin that promote the occurrence of cardio-metabolic syndrome and hypertension in obesity." (PMID 38541059, 2024).